SLC44A1 (solute carrier family 44 member 1)
Description:
Choline/H+ antiporter. Also acts as a high-affinity ethanolamine/H+ antiporter, regulating the supply of extracellular ethanolamine (Etn) for the CDP-Etn pathway, redistribute intracellular Etn and balance the CDP-Cho and CDP-Etn arms of the Kennedy pathway. Involved in membrane synthesis and myelin production.
Synonyms: CD92; CDW92; CTL1; CHTL1; CONATOC
Tractability: Small molecule: a structure with a bound ligand is known. Antibody: UniProt places it where antibodies can reach, with high confidence; its Gene Ontology location is reachable by antibodies, with high confidence; UniProt predicts a signal peptide or a membrane-spanning region. PROTAC: ubiquitination databases record sites on it; its protein half-life has been measured.
Target class: Transporter
Gene: Protein-coding gene on chromosome 9 (105,244,536 to 105,439,171, forward strand). Ensembl gene ENSG00000070214.
Subcellular location: Cell membrane; Mitochondrion outer membrane
Subcellular location (Human Protein Atlas): Mitochondria; Nucleoplasm
Pathways (Reactome):
Metabolism: Choline catabolism; Synthesis of PC
Transport of small molecules: SLC-mediated bile acid transport
Gene Ontology:
Molecular function: choline transmembrane transporter activity; ethanolamine transmembrane transporter activity; transmembrane transporter activity
Biological process: choline transport; ethanolamine transport; transmembrane transport; bile acid and bile salt transport; choline catabolic process; phosphatidylcholine biosynthetic process; transport across blood-brain barrier
Cellular component: cytosol; extracellular exosome; membrane; mitochondrial outer membrane; mitochondrion; plasma membrane
Genetic constraint (gnomAD): Loss-of-function variants: 12 observed, 44.51 expected, observed/expected ratio (o/e) 0.27, 90% interval 0.17 to 0.44. The upper end of that interval is the gene's LOEUF score, 0.44, which puts it in group 1 of 6, group 1 being the genes least tolerant of losing a copy. Missense variants: 440 observed, 540.2 expected, observed/expected ratio (o/e) 0.81, 90% interval 0.75 to 0.88. Synonymous variants: 173 observed, 195.91 expected, observed/expected ratio (o/e) 0.88, 90% interval 0.78 to 1.
Homologues: Orthologues: macaque SLC44A1 (99% identical), chimpanzee SLC44A1 (98% identical), mouse Slc44a1 (95% identical), pig SLC44A1 (95% identical), rat Slc44a1 (94% identical), guinea pig SLC44A1 (93% identical), dog SLC44A1 (93% identical), rabbit SLC44A1 (87% identical), tropical clawed frog slc44a1 (84% identical), zebrafish slc44a1b (74% identical). Paralogues in human: SLC44A3 (47% identical), SLC44A2 (29% identical), SLC44A5 (29% identical), SLC44A4 (27% identical).
Diseases named in the same sentence as SLC44A1 in open-access papers:
SLC44A1 is named in the same sentence as 60 diseases in open-access papers, as found by Europe PMC text mining. Sharing a sentence is not in itself a finding about the gene and the disease. The quoted sentences say what the papers report.
glioma (5 papers, 2017 to 2025). A benign or malignant brain and spinal cord tumor that arises from glial cells (astrocytes, oligodendrocytes, ependymal cells). "The SLC44A1-PRKCA fusion, characterized in this study, was identified in rare mixed neuronal-glial tumors known as PGNTs that are difficult to diagnose." (PMID 33617877, 2021).
papillary glioneuronal tumor (4 papers, 2015 to 2022). A WHO grade I, indolent and relatively circumscribed brain tumor. "Besides, high activity of the SLC44A1 promoter has been proved to participate in the occurrence of papillary glioneuronal tumors." (PMID 36046013, 2022). "The 3' fusions TANC2-PRKCA, SLC44A1-PRKCA, and GGA2-PRKCB, found in lung squamous cell carcinoma (LUSC), papillary glioneuronal tumors (PGNT), and low-grade glioma (LGG), respectively, were selected for biochemical analysis." (PMID 33617877, 2021).
ganglioglioma (2 papers, 2015 to 2025). A well differentiated, slow growing neuroepithelial neoplasm composed of neoplastic, mature ganglion cells and neoplastic glial cells. "Interestingly, the two gangliogliomas with pseudopapillary features, which are negative for SLC44A1-PRKCA fusion, were BRAF mutation immunopositive." (PMID 26671581, 2015).
glioneuronal tumors (2 papers, 2015 to 2024). "The current study aimed at raising the cytogenetic, histological and molecular profiles of PGNT and to determine if SLC44A1-PRKCA fusion represented a specific diagnostic marker to distinguish it from other glioneuronal tumors." (PMID 26671581, 2015). "We present the first report of the spatial and temporal co-occurrence of an intracranial arteriovenous malformation traversing and within a papillary glioneuronal tumour, molecularly defined by the presence of SLC44A1::PRKCA fusion." (PMID 39292231, 2024). "Histologically and immunohistochemically, PGNT is not readily differentiated from other glioneuronal tumours; however, SLC44A1::PRKCA fusion appears to be unique to PGNT and is now regarded as its defining molecular feature." (PMID 39292231, 2024).
pancreatic adenocarcinoma (2 papers, 2020 to 2021). "The survival analysis in pancreatic adenocarcinoma demonstrates a high survival probability of individuals with medium/low expression level of SLC44A1 than in individuals with high expression levels." (PMID 34439361, 2021). "Indole-3-carbinol affects the expression of 5 different genes (CD47, CENPB, ERGIC1, PPRC1, SLC44A1) that, in turn, affect the survival in patients with uterine corpus endometrial carcinoma (CD47), brain lower-grade glioma (CENPB, ERGIC1) and pancreatic adenocarcinoma (PPRC1, SLC44A1), respectively." (PMID 34439361, 2021).
pancreatic cancer (2 papers, 2020 to 2024). "KIAA1217, SLC44A1, INPP5B, and SDK1 were reversely correlated with some miRNAs not affecting patient survival, which shows these are potential therapeutic targets for pancreatic cancer." (PMID 38741142, 2024).
viral infection (2 papers, 2021 to 2022). "This combined epigenetic and transcriptomic approach allowed for the proposal of candidate genes (e.g., DUSP10 encoding dual specificity phosphatase 10 and SLC44A1 encoding solute carrier family 44 member 1) for asthma and viral infection susceptibility." (PMID 33668787, 2021). "SLC-mediated transporters for thyroid hormone, ions, amino acids, choline, and energetic substrates (e.g., SLC16A2, SLC41A3, SLC16A10, SLC44A1, and SLC35C2) were downregulated following viral infection." (PMID 36314791, 2022).
astroblastoma (1 paper, 2015). "In our cohort, none of ANETs, RGNTs, PRPs, PE, astroblastoma, neurocytomas studied showed the SLC44A1-PRKCA fusion, further supporting PGNT as a unique entity." (PMID 26671581, 2015).
bone metastasis (1 paper, 2022). Transfer of a neoplasm from its primary site to bones. "In the validation dataset of GSE14020, GJA1, IGFBP6, ITGBL1, SLC44A1, and TGFBI expressions in the bone-metastasis group were different from those in the control group." (PMID 36046013, 2022).
colon cancer (1 paper, 2021). "SLC44A1 may be involved in the tumorigenesis and the metastasis of colon cancer, and is currently used as a prognostic biomarker." (PMID 34550272, 2021).
glaucoma (1 paper, 2024). Increased pressure in the eyeball due to obstruction of the outflow of aqueous humor. "Regarding the genetic aspect, SNPs with high OR values for glaucoma exposure on cataract were TMCO1-AS1 (rs2814471 with OR = 1.370), GAS7 (rs12602519 with OR = 1.178), ABCA1;SLC44A1 (rs2472493 with OR = 1.162), and GNB1L;TXNRD2 (rs58714937 with OR = 1.153)." (PMID 38674349, 2024).
head and neck cancer (1 paper, 2020). A primary or metastatic malignant neoplasm affecting the head and neck. "Specifically, for head and neck cancer, the expression levels of three genes, NFE2L2, RMND5A and SLC44A1, were associated with increased smoking-related mutational signature, while an inverse association was observed for one gene, ARRB1." (PMID 32928150, 2020).
insomnia (1 paper, 2021). A sleep disorder characterized by difficulty in falling asleep and/or remaining asleep. "SNPs rs117615688 in CRHR1 and rs382940 in SLC44A1 are associated the non-motor symptoms of insomnia and restless leg syndrome (RLS), respectively." (PMID 33935957, 2021).
liver dysfunction (1 paper, 2017). "While the majority of people present with liver dysfunction in response to choline deprivation, Zeisel and colleagues noted that some individuals present first with muscle dysfunction, and they tend to carry mutations in the SLC44A1 gene." (PMID 28134761, 2017).
cancer (16 papers, 2015 to 2025). A tumor composed of atypical neoplastic, often pleomorphic cells that invade other tissues. "SLC44A1, a choline transporter-like protein, is overexpressed in various cancer cell lines." (PMID 38741142, 2024). "Finally, the gene SLC44A1 is down-regulated under Tamoxifen apoptotic treatment, Indole-3-Carbinol and Withaferin A nutrigenomics treatments, while it is up-regulated in 12 different types of cancers." (PMID 34439361, 2021). "A number of these genes, including ACYP1, MFF, SLC44A1, and HFE, promote cancer development by regulating metabolic pathways." (PMID 40503897, 2025).
tumor (13 papers, 2015 to 2026). "In conclusion, miR-8485-mediated downregulation of UBN2, ETS1, MMS22L, GSK3B, and SLC44A1 inhibits tumor progression through mechanisms involving cell cycle arrest, metastasis inhibition, apoptosis induction, and choline metabolism." (PMID 40095604, 2025). "FISH analysis conducted on representative FFPE tissue sections of all PGNTs revealed a fusion of SLC44A1-PRKCA in a high percentage of the tumor nuclei examined, indicating a rearrangement of these loci." (PMID 26671581, 2015). "Finally, miR-8485 downregulates SLC44A1, a key choline transporter, inhibiting tumor progression by reducing choline uptake." (PMID 40095604, 2025). "We found that SLC44A1 is specifically expressed in fibroblasts of NB tissues, indicating that sEVs containing this protein may mediate communication between fibroblasts and tumor cells or other cells in the NB tumor microenvironment." (PMID 39228987, 2024). "Comprehensive genome profiling showed a novel SLC44A1-BRAF fusion and the tumor progression was controlled with the MEK inhibitor trametinib." (PMID 38523924, 2024).
neurodegenerative disease (5 papers, 2019 to 2023). A disorder of the central nervous system characterized by gradual and progressive loss of neural tissue and neurologic function. "Although there have been no reports of diseases due to CTL1 failure, a new neurodegenerative disease caused by frameshift mutations in the SLC44A1 gene encoding CTL1 was recently described." (PMID 33672580, 2021).
SLC44A1 also shares sentences with these, for which no sentence is quoted: infection (10 papers); neuroblastoma (3); toxocariasis (3); helminth infection (2); inflammatory brain diseases (2); leukemia (2); lung adenocarcinoma (2); lung carcinoma (2); AIDS (1); alcohol use disorders (1); Alzheimer disease (1); amebiasis (1); asthma (1); Ataxia (1); brain tumors (1); breast carcinoma (1); Burkitt lymphoma (1); cognitive decline (1); COVID-19 (1); esophageal cancer (1); follicular lymphoma (1); hepatocellular carcinoma (1); liver disorder (1); liver steatosis (1); low grade glioma (1); lung squamous cell carcinoma (1); Motor Neuron Disease (1); myopathies (1); neurocytomas (1); optic atrophy (1).
A further 13 diseases each share a sentence with SLC44A1 in 1 paper.